EGF (epidermal growth factor)
Diseases named in the same sentence as EGF in open-access papers (continued):
Sharing a sentence is not in itself a finding about the gene and the disease.
tumor (continued). "Memo KD tumor cells showed decreased migration upon treatment with EGF, HRG or FGF." (PMID 24714781, 2014). "Previous report showed that epidermal growth factor (EGF) promotes tumor progression." (PMID 25122478, 2014). "So, it is suggested that these events lead to the establishment of an EGF-dependent autocrine loop which could favour a switch towards a tumour cell-autonomous mechanism and here allow growth factors independent cell growth and proliferation." (PMID 24796332, 2014). "EGF-induced biochemical changes within the cell ultimately lead to DNA synthesis and cell proliferation, cell division, wound healing, carcinogenesis and tumour progression 17,25." (PMID 24268047, 2014). "Despite the fact that the identified genes were relatively cell line-specific, induction of some EGF pathway-related transcripts in the analyzed cell lines suggests that this molecular pathway may be involved in the tumor cell response to cycling hypoxia." (PMID 25122487, 2014). "Furthermore, it is conceivable that a wide range of tumour-specific targets, such as epidermal growth factor (EGF), can be applied to HDL-like NPs." (PMID 24564841, 2013). "Studies have shown that interruption of EGF signaling impairs tumor growth." (PMID 23251236, 2013). "Emerging clinical data suggest that intra-tumor let-7a expression correlates with tumor response and overall survival in metastatic colorectal cancer patients receiving epidermal growth factor (EGFR) targeting agents in both KRAS wild-type and mutant populations." (PMID 23936455, 2013). "In addition, Claudin-2, a unique member of the claudin family of transmembrane proteins which is significantly increased in CRC and correlates with cancer progression and tumour growth, is regulated in Caco-2 via EGF." (PMID 24180698, 2013). "Overall, our results suggest that some of the cancer cells that were stimulated by TNFα + Estrogen + EGF partly succumbed to the cytotoxic effects of TNFα and others migrated out of the initial tumor inoculum, giving rise to smaller primary tumors than those generated by control cells." (PMID 24369447, 2013). "However, the roles that EGF plays in modulating the expression of these proteins are different and depend of the cell type and tumor." (PMID 24069372, 2013). "Moreover, to follow on the cell-remodeling, EMT, and metastatic/invasive properties acquired by tumor cells that were exposed to the combined stimulation by TNFα + Estrogen + EGF, we determined the migratory functions of the cells." (PMID 24369447, 2013). "In contrast, the MMP19 transcript, whose relevant protein is associated with invasion and tumor progression, was not up-modulated in EGF-stimulated EOC cells." (PMID 23889749, 2013). "A special role was highlighted for CSF-1, which is secreted from tumor cells and helps recruit macrophages and sustain them in the tumoral microenvironment, and to EGF, which is secreted from the infiltrating macrophages and serves to induce tumor cell migration and invasion." (PMID 23785333, 2013). "Lrig1 is a tumor suppressor gene required for normal EGF signaling." (PMID 24086156, 2013). "According to the well-documented role of MMP-7, IL-8, and VEGFA for cancer development and tumor growth, synergistic effects between HH/EGF mediated signaling pathways may accelerate tumor initiation and support tumor growth." (PMID 23762360, 2013). "Additionally, the ERK1/2 and PI3K pathways have been reported to mediate increases in EGF-induced claudin-2 expression in colon cancer cells; this event was accompanied by increases in proliferation, anchorage-independent growth and tumor growth in vivo." (PMID 24069372, 2013). "Moreover, although TNFα was cytotoxic to some of the tumor cells, its cooperativity with estrogen and EGF has led to selection of tumors cells that have gained high metastasizing abilities in vivo, in an animal model system." (PMID 24369447, 2013).
tumor (continued). "Therefore, the small tumor growth endowed following TNFα + Estrogen + EGF stimulation provided a false benefit, because it has led to selection of cells expressing a higher metastasizing potential." (PMID 24369447, 2013). "As a result of TNFα + Estrogen + EGF stimulation, new cell subtypes have dominated the tumor cell population, expressing high levels of VLA6 and of the metastasis-related adhesion molecules CD44 and β1, accompanied by high levels of CXCL8, CCL2, and MMPs that were released by the cells." (PMID 24369447, 2013). "Therefore, in more advanced stages of the research we focused on the effects of the joint stimulation by TNFα + Estrogen + EGF on functional tumor-promoting readouts, including tumor growth and metastasis formation." (PMID 24369447, 2013). "The results described here suggest that the levels of 3 specific tumor proteins (Ang1, EGF, Emmprin) taken together as a multi-expression signature may be predictive of anti-Ang2 therapy in XG models." (PMID 24244628, 2013). "Moreover, TAMs are necessary for metastasis, and their ability to secrete EGF together with the ability of tumor cells to secrete M-CSF/CSF-1 stimulate mutual migration in both cell types." (PMID 23785333, 2013). "In this way, the evaluation of EGF expression on both serum and tumor section using the CB-EGF1 Mab could lead to a better selection of NSCLC patients to CIMAVax-EGF therapy." (PMID 26317020, 2013). "Altogether, the studies reported here indicate that the combination of PDT with EGF-SubA cytotoxin generates synergistically enhanced cytotoxicity toward tumor cells, and in two investigated cell lines it leads to an unusual type of tumor cell death accompanied by massive cytoplasmic vacuolation." (PMID 23887632, 2013). "Although the functional role of IL-1β in the regulation of tumorigenesis, tumor invasiveness, metastasis, and tumor-host interactions has been characterized, the main role of EGF-induced IL-1β expression remains unclear." (PMID 23383347, 2013). "The aim of this study was to investigate whether stimulation with recombinant epidermal growth factor (EGF) or serotonin leads to an increased tumor cell proliferation in xenografts." (PMID 22825751, 2012). "In the absence of EGFR mutations in tumor cells, we hypothesized that receptor stimulation might depend on the production of high EGF levels in the tumor microenvironment." (PMID 23056514, 2012). "Importantly, following EGF treatment, we detected elevated transcript levels of several MUC1 target genes linked to tumor cell invasion including TWIST, SNAI1, and SNAI2." (PMID 22586492, 2012). "Therefore, a decrease in EGF mRNA coupled with inhibition of tyrosine kinase by genistein would profoundly decrease tumor growth as cell signaling pathways are crucial to tumor maintenance." (PMID 22187555, 2012). "The exposure of tumor cells to low concentrations of EGF stimulates cells migration." (PMID 22790341, 2012). "Thus induction of TTP expression by EGF can be classified as a anti-tumor activity of this growth factor." (PMID 22433566, 2012). "EGF is well-known as a factor which promotes tumor growth and survival." (PMID 22433566, 2012). "TGF-β and EGF are growth factors that can induce tumor progression by means of the ERK pathway." (PMID 22046506, 2012). "Furthermore, images of dissected tissues demonstrated accumulation of EGF-NIR in the tumor and liver." (PMID 23144978, 2012). "The aim of this study was to investigate whether tumor cell stimulation with EGF and 5-HT can affect tumor growth in xenografts." (PMID 22825751, 2012). "In the case of many carcinomas, EMT-inducing signals, such as HGF, EGF, PDGF, and TGF-β, emanate from the tumor-associated stroma and activate a series of EMT-inducing transcription factors, including Snail, Slug, zinc finger E-box binding homeobox 1 (ZEB1), Twist, Goosecoid, and FOXC2." (PMID 22479362, 2012).
tumor (continued). "Furthermore, exposure of GB cells to EGF, a factor that promotes migration and invasion of normal and tumor cells, induces phosphorylation (activation) of NKCC1 through PI3K-Akt-WNK3 pathway." (PMID 22570591, 2012). "This is an important prerequisite to model and to understand, how EGF-dependent cell motility contributes to tumor cell behavior and may thus help to identify specific tumors that are suitable targets for anti-EGF receptor-based therapies." (PMID 23028903, 2012). "Well-known examples include antibodies that target tumor expressing receptors for epidermal growth factor (EGF), called Herceptin, those that target HER-2, and those that are directed against angiogenic, tumor blood vessel growth-promoting vascular endothelial growth factor (VEGF), known as Avastin." (PMID 24955288, 2012). "The results of these studies indicate that the tumor cells are not activated through autocrine stimulation by CXCL12, but rather that a paracrine loop involving CXCR4-CXCL12 signaling in the tumor microenvironment is needed for EGF-induced in vivo invasion in Neu-YB tumors." (PMID 22314082, 2012). "Cytokine secretion seemed to rely upon the location where superantigen-activated T lymphocytes adhered and proliferated, demonstrating that the targeting of tumor-infiltrating CTLs by EGF-SEA was required for the restriction of cytokine cytotoxicity to the tumor site." (PMID 21311755, 2011). "Th2 lymphocytes can enhance the spread of tumor cells to distal sites via the activation of TGF-β- and EGF-expressing tumor-associated macrophages suggesting that a Th2-polarized immune response may promote tumor cell dissemination." (PMID 21283768, 2011). "In addition to this local increase in cytokine secretion in treated tumor, immunohistochemistry analysis showed that Fas expression was upregulated and largely restricted in the tumors treated with EGF-SEA." (PMID 21311755, 2011). "Additionally, EGF hybrids carrying pseudomonas exotoxin or ribonuclease displayed selective cytotoxicity against tumor cells bearing elevated EGFRs." (PMID 21311755, 2011). "In total, we obtained 266 “tumor-EGF-network” PWMs yielding 31,306 pairwise combinations." (PMID 21464922, 2011). "In contrast, the protein did not persist in other organs except the bladder containing traces of excreted or degraded EGF-SEA proteins, indicating that only the tumor had highly affinity for EGF-SEA and acted as a reservoir in which EGF-SEA molecules flowing through blood vessels were stored." (PMID 21311755, 2011). "Overall, we hypothesize a switch in autocrine signaling to foster tumor growth that was initially triggered by EGF." (PMID 21464922, 2011). "Therefore, we sought TFs downstream from EGF whose binding sites were enriched in promoters of upregulated tumor genes." (PMID 21464922, 2011). "Thus, there were 18 hrs for S180 cells to develop into a growing tumor before the arrival of EGF-SEA." (PMID 21311755, 2011). "This might indicate a stronger dependence of early tumour grades on EGF pathway signalling to maintain HAS3 activity." (PMID 21429221, 2011). "In particular, it has been shown that tumor-associated macrophages secrete epidermal growth factor, but the normal or malignant breast cancer cells do not." (PMID 21747968, 2011). "We stimulated tumor cells with EGF of different concentrations." (PMID 23554613, 2010). "Previous studies in PyMT mice illustrate the contribution of the microenvironment to metastatic potential and describe a paracrine loop whereby invasion, intravasation and metastasis involve signaling between macrophages and tumor cells where these cells secrete EGF and CSF1 respectively." (PMID 21108830, 2010). "Our results from pre-surgery patients suggest that the impaired ability to heal oral mucosa damage in neoplastic diseases may be related to the low EGF concentration in the saliva." (PMID 20429940, 2010).
tumor (continued). "Furthermore, the study of invasion, intravasation and metastasis using both methods has shown the involvement of a paracrine loop between macrophages and tumor cells that secrete EGF or colony stimulating factor-1 (CSF1), respectively." (PMID 21108830, 2010). "Finally, we will discuss several recent findings that established a role for EGF signalling in the complex network of tumour–stromal cross talks during the formation of osteolytic bone metastasis." (PMID 20010942, 2010). "These genes are involved in the regulation of immune/inflammatory response (Lgals1, Ptgds, Tff2, Ubd), tumor angiogenesis (Lgals1, Esm1, Ndrg1), epidermal growth factor signaling (Erbb4, Nrg1), response to tissue injury (Tff2, Vnn1), and gene transcription (Id3, Ifrd1)." (PMID 19340302, 2009). "We hypothesize that α6β4 integrin clustering at the leading edge of a tumor might lead to a redistribution and concentration of EGFR at the invading front, thereby promoting the motility of tumor cells towards an EGF gradient." (PMID 19470173, 2009). "Interestingly, all of the patients (N=11) having EGFR tumour expression detected by immunohistochemistry together with low levels of both serum EGF (<667 pg ml−1) and TGF-α (<14 pg ml−1) showed a response." (PMID 19127259, 2009). "The overexpression of epidermal growth factor (EGF) and epidermal growth factor receptors (EGFR) were observed in HCC, being associated with late-stage disease, increased cell proliferation and degree of tumor differentiation." (PMID 27942274, 2009). "The presence of HGF and EGF in vivo, may have an impact on growth later phase growth (past day 8) or likewise in other tumor models." (PMID 19352430, 2009). "After homing to the lung vasculature, therefore, tumor cells with EGFR clustering might undergo an augmented response to EGF, favoring directed motility towards EGF in the adjacent lung tissue." (PMID 19470173, 2009). "In addition, there was experimental evidence that both macrophages and tumour cells were necessary and sufficient for comigration and invasion by a colony-stimulation factor-1/EGF paracine loop." (PMID 18283317, 2008). "The formation of macropinosomes is largely a signal dependent process that is transiently induced by growth factors such as macrophage colony-stimulating factor (M-CSF) and epidermal growth factor (EGF) or tumour promoting factors such as phorbol myristate acetate (PMA)." (PMID 18854019, 2008). "Furthermore, it has been reported that EGFR-HER-2 heterodimers are rate-limiting in the EGF-mediated proliferation of tumour cells." (PMID 17622245, 2007). "The study of the relationship between the serum levels of sEGFR and EGF and TGF-α and AR and the clinicopathological features of the patients demonstrated a significant association between the decrease of sEGFR levels and the tumour stage (P=0.011)." (PMID 17453000, 2007). "Thus, inhibition of PLC-γ1 activity is an appropriate way to block EGF-driven tumour cell migration and invasiveness." (PMID 14710234, 2004). "Since PLC-γ1 is a key player in the EGF-mediated induction of tumour cell migration, we next analysed the migratory behaviour of PS1/2-TAT-treated MDA-HER2 cells by using the three-dimensional collagen matrix migration assay combined with computer-assisted cell tracking." (PMID 14710234, 2004). "The tumour weight of A431, both estimated and measured in sialex mice, was significantly lower than that in sham-operated control mice (P < 0.05), and the growth of A431 tumour was significantly increased by exogenous EGF treatment (P < 0.05)." (PMID 7547232, 1995). "Accordingly, an anti-EGF antibody was tested as a putative inhibitor of tumour growth as any effect of this antibody could be ascribed to removal of EGF derived from the host." (PMID 8054274, 1994).
tumor (continued). "Athymic mice bearing xenografts of human tumours that overexpress the receptor (EGFR) for EGF and TGF alpha have been used to evaluate the therapeutic potential of three new rat monoclonal antibodies (mAbs) directed against two distinct epitopes on the extracellular domain of the human EGFR." (PMID 7679281, 1993). "EGF expression was seen statistically more frequently in well differentiated tumours." (PMID 2544220, 1989). "In addition to lactate production by tumor cells through the Warburg effect, the secretion of LGALS9 (encoding the galactoglucan lectin-9 protein, Gal-9) and epidermal growth factor (EGF) by tumor cells is essential for inducing the polarization of TAMs into M2 TAMs." (PMID 39889181, 2025). "Taken together with previous findings on their differential expression in BRCA and other malignancies, these data support the notion that CCL18 and EGF not only serve as markers of tumor biology but may also actively influence immune cell dynamics and tumor–immune interactions." (PMID 40692603, 2025). "Therefore, the inhibition of the CSF-1 or EGF signaling pathway may have promise to disrupt the migration of both cell types and reduce the number of circulating tumor cells (CTCs)." (PMID 39003350, 2024). "In breast cancer, M2-type macrophages are widely regarded as the predominant type of tumor-associated macrophages, and are also considered to be broadly defined as TAMs, which support tumor growth through the secretion of growth factors such as TGF-β, VEGF, and EGF." (PMID 39697553, 2024). "Interestingly, we found that XAF1 is a novel substrate of TRIM28 and that EGF-induced TRIM28 protects tumor cells from etoposide-induced apoptosis more significantly in XAF1+/+ versus XAF1−/− cells, indicating that TRIM28 exerts anti-apoptotic effect in a highly XAF1-dependent fashion." (PMID 39532800, 2024). "Similarly, LOX can activate epidermal growth factor (EGF) signaling to drive tumor metastasis." (PMID 39766266, 2024). "Additionally, EGF has been shown to support tumor cell motility, adhesion, and metastasis." (PMID 39590368, 2024). "Moreover, EGF derived from CAFs under ascitic tumor cell stimulation is significantly enriched within heterotypic spheroids, where it increases integrin α5 expression on ascitic tumor cells, thereby strengthening interactions between ascitic tumor cells and CAFs." (PMID 39513610, 2024). "Importantly, α-granules serve as a primary reservoir for angiogenic factors such as VEGF, platelet-derived growth factor (PDGF), epidermal growth factor (EGF), and basic fibroblast growth factor (bFGF) through which, platelets stimulate angiogenesis in the tumor microenvironment (TME)." (PMID 39114075, 2024). "TAMs promote tumor angiogenesis by secreting a plethora of pro-angiogenic growth factors, cytokines, and chemokines that induce EC proliferation and migration, including EGF, FGF-2/bFGF, platelet-activating factor (PAF), PDGF, VEGF, TNF-α, IL-1, IL-8/CXCL8, and CCL18." (PMID 38580870, 2024). "Additionally, macrophage secretion of EGF induced by CCL2 promotes ESCC tumor growth." (PMID 39596630, 2024). "Moreover, EGF’s involvement in tumorigenesis extends to tumor migration as well." (PMID 38539448, 2024). "Our observation is consistent with prior results demonstrating EGFR-YAP/TAZ signaling interplay during tumor progression, and further strengthens the fact that mechanical stimulation can drive changes in the EGF/EGFR signaling pathway impacting the oncogenic activity of TNBC." (PMID 36968199, 2023). "Moreover, epidermal growth factor (EGF) and suitable monoclonal antibodies are regarded as effective targeting agents for the surface modification of GNPs, as they allow the specific recognition of tumor cells." (PMID 36839641, 2023). "Also, EGF secretion by TAMs may activate EGFR on tumor cells, further upregulate VEGF/VEGFR signaling, and thus increase cancer cell proliferation and invasion." (PMID 38033495, 2023).